ALB (albumin)
Diseases named in the same sentence as ALB in open-access papers (continued):
Sharing a sentence is not in itself a finding about the gene and the disease.
Cirrhosis (continued). "Overall, most patients with HH were at the more extreme end of the severity spectrum of decompensated cirrhosis, with significantly lower GGT, CHE, serum ALB, and PTA compared to the non-HH group." (PMID 36148461, 2022). "In question 5, 20.5% (n = 18) would administer albumin in patients with non-SBP infections/septic shock and cirrhosis." (PMID 33270161, 2021). "In addition, considering that long-term albumin administration improves survival in patients with cirrhosis, such treatment may also be a promising therapeutic option for preventing HCC recurrence in pre-S2 mutant-positive HCC patients who have a low serum albumin level." (PMID 34575311, 2021). "Studies about celiac and cirrhosis are not prevalent, so we conducted this study to evaluate a change in patient MELD-Na and albumin level from the time of celiac disease diagnosis to six months later, after implementing a gluten-free diet." (PMID 32582496, 2020). "Therefore, VCTE above this cut-off may not be enough to confirm the presence of cirrhosis, reflects from the baseline laboratory results of our patients, the median serum albumin and platelet count were 4.3 g/dL and 172 x 109/L, respectively, which are corresponding to mild-to-moderate fibrosis." (PMID 32106270, 2020). "This study reproduced a previous finding that liver function, as represented by serum albumin level, improved with SVR in patients with and without cirrhosis." (PMID 32310974, 2020). "Patients with cirrhosis were older, more often male, had higher AST, ALT, and bilirubin levels, as well as prothrombin time and showed lower albumin and platelet levels than those without cirrhosis." (PMID 26696302, 2015). "AOPPs-albumin plasma concentration was significantly higher in cirrhotic patients (n = 88; median 2.4 μmol/g, IQR 1.3–5.2 μmol/g) compared to CHC patients without cirrhosis (n = 32; median 2.1 μmol/g, IQR 0.9–3.0 μmol/g) (P < 0.05)." (PMID 26665009, 2015). "Our data showed that if these four serum markers ALP, bilirubin, albumin and platelet count are used simultaneously, they have high PPV and NPV for predicting cirrhosis and differentiating no/minimal fibrosis from significant fibrosis." (PMID 21507271, 2011). "This study also highlights that serum 25(OH)D3 and albumin levels, which are predictors of CHE, are important and readily available factors in the management of patients with cirrhosis, without the factor of the presence of esophageal varices diagnosed by upper gastrointestinal endoscopy." (PMID 40142666, 2025). "This may be because albumin specificity increases for MASH, advanced fibrosis, or cirrhosis rather than for MASLD alone." (PMID 41026784, 2025). "Therefore, this study focuses on ICU patients with cirrhosis and non-HRS AKI to explore the impact of albumin infusion on patient outcomes." (PMID 39434907, 2024). "This small difference between the groups was not significant; the investigators concluded that, in patients hospitalized with decompensated cirrhosis, HSA infusions to increase the albumin level to a target of 3 g/dL or more are not more beneficial than the current standard care in the UK." (PMID 37013893, 2023). "It is not surprising that in our study, patients with HE had not only a significantly higher prevalence of spontaneous porto-systemic shunts assessed by CT but also significantly lower albumin levels, lower BMI, and higher MELD score compared with patients with decompensated cirrhosis without HE." (PMID 37305121, 2023). "Furthermore, chronic conditions such as cirrhosis, nephritic syndrome decreased DBP and albumin level but free 25 (OH) vitamin D level was not alter." (PMID 33709027, 2021). "However, we did not notice any difference in albumin titre and INR between the UK Asians and Caucasians in our study, as the majority of cases are compensated Child-Pugh grade A cirrhosis." (PMID 27101826, 2016).
Cirrhosis (continued). "The analysis within patients with cirrhosis without HCC revealed significant differences between patients in the CPS A vs B/C groups regarding Creatine, Dimethysulfone, Valine, HDL_p, HDL_A_c, HDL_B_c, HDL_C_c, Total Cholesterol, Alanine, Albumin, and Total Bilirubin." (PMID 40183893, 2025). "In addition, transferrin, BCHE, and apolipoprotein AI but not albumin and transthyretin display a stage-dependent decrease of serum concentrations from stable (SDC) and unstable decompensated cirrhosis (UDC) to pre-ACLF and ACLF as indicated by a significant Jonckheere-Terpstra test." (PMID 36652164, 2023). "Moreover, higher relative abundance levels of miR-29b-3p and miR-29c-3p were observed in patients with a higher MELD-Albumin score ≥ 11 and ALBI score > −2.6 both indicating advanced liver fibrosis/cirrhosis as well as in patients with incomplete or no Fontan palliation." (PMID 33490119, 2020). "Compared with patients without HCC, the HCC group had significantly lower serum albumin and platelet count but higher serum total bilirubin, aspartate aminotransferase (AST), alanine aminotransferase (ALT), AFP level, the presence of HBV genotype C and cirrhosis." (PMID 32330203, 2020). "Of the patients with baseline cirrhosis, none were Child-Pugh B or C, none had a history of a decompensating event (e.g., hepatic encephalopathy, ascites), and none had two or more of the following laboratory abnormalities: INR ≥1.7, total bilirubin ≥2 mg/dl, or albumin ≤3.5 g/dl." (PMID 25788199, 2015).
liver disease (830 papers, 2005 to 2026). "In contrast, the PALBI score incorporates platelet count in addition to albumin and bilirubin, providing a more comprehensive assessment of the dual damage of “liver function + portal hypertension” caused by liver cirrhosis." (PMID 40936688, 2025). "BCLC-C patients also had a higher prevalence of HCV as the underlying etiology of liver disease (95% vs. 59%), but all measures of preserved liver function (Child-Pugh, albumin, and bilirubin) remained well controlled." (PMID 40940842, 2025). "The progressive decline in serum albumin and platelet count mirrors hepatic synthetic dysfunction and portal hypertension, respectively, both hallmark features of cirrhosis." (PMID 40550831, 2025). "The addition of albumin to create the FIB-4+ score is predictive of clinically significant portal hypertension in patients with metabolic dysfunction–associated steatotic liver disease." (PMID 40131017, 2025). "Although albumin did not have a statistically significant relationship with HU score, the median and mean albumin levels were below the normal range, indicating that the patient cohort experienced nutritional deficiencies, as expected, given the liver disease." (PMID 40225556, 2025). "According to Hunchak (2024), albumin fluctuations generally indicate pathological states (e.g., chronic infections, protein loss, liver disease), whereas the A/G ratio remains stable in healthy animals." (PMID 41012839, 2025). "Given the well-established roles of bilirubin and albumin in determining mortality risk, it is reasonable to infer that the B/A ratio also correlates with mortality, particularly in patients with liver disease." (PMID 41428744, 2025). "Alterations in albumin structure and function have been implicated in various chronic conditions, including liver disease and metabolic syndromes." (PMID 41180192, 2025). "In our cohort, PV‐1 was associated with the severity of liver disease, that is, compensation/decompensation status, albumin, platelet count, INR and bilirubin, but also with inflammatory markers such as WBC count and the acute phase proteins CRP and LBP." (PMID 40317887, 2025). "Metabolic liver adaptations related with aging process are not well understood, but biochemical changes in LDH and albumin levels have been linked to liver diseases." (PMID 38923278, 2024). "Serum albumin levels can be affected by various conditions, such as advanced liver disease, dilution caused by fluid balance, edema, nephrotic syndrome, and cancer." (PMID 39557984, 2024). "Metabolic liver adaptations related to aging are poorly understood, but biochemical changes in LDH and albumin levels have been linked to liver diseases." (PMID 37897241, 2024). "The American Association for the Study of Liver Diseases' 2021 practice guidance also recommends the use of albumin in the management of SBP to prevent AKI progression." (PMID 38899040, 2024). "The 2009 and 2012 American Association for the Study of Liver Diseases' practice guidelines recommend that SBP be managed with administration of albumin." (PMID 38899040, 2024). "One way in which hepatic disease can cause bilateral edema is through the impairment of the liver’s ability to synthesize albumin." (PMID 39099956, 2024). "IV albumin should be administered at the time of paracentesis to reduce the risk of hepatorenal syndrome (HRS)." (PMID 38534970, 2024). "Since albumin is mainly produced in the liver, all types of liver disease that are associated with reduced albumin production lead to a decrease in serum albumin levels." (PMID 39292095, 2024). "No sub-analysis was performed to identify the baseline characteristics that favored hepatic decompensation after SVR but advanced fibrosis, CSPH, and albumin levels < 3.5 mg/dL were found to be risk factors for liver disease progression." (PMID 36983196, 2023).
liver disease (continued). "In clinical practice, serum albumin levels are associated with granular degeneration of the liver and are considered to be an important indicator of liver disease." (PMID 38274659, 2023). "Albumin is a well-established therapy in patients with liver disease (e.g., advanced liver cirrhosis), reducing the risk of death up to 38% compared to those who received standard medical therapy." (PMID 37888650, 2023). "Low albumin levels have been linked with hepatic disorders, which can potentially impact the metabolism process." (PMID 40980094, 2023). "This agrees with the fact that life expectancy depends not only upon tumor treatment efficacy but also on the underlying severity of liver disease, especially in patients with low albumin levels." (PMID 37090102, 2023). "Another study identified that abnormal serum albumin and total bilirubin concentrations were associated with an increased risk of liver disease." (PMID 36767787, 2023). "As for etiology, MSCs therapy was associated with increased ALB levels at 4 weeks, 24 weeks and 48 weeks in patients with liver disease caused by HBV." (PMID 35578365, 2022). "Terlipressin with albumin, the recommended treatment for hepatorenal syndrome-acute kidney injury (HRS-AKI), is associated with adverse events." (PMID 35365736, 2022). "Due to albumin's oncotic properties, treating liver cirrhosis with albumin has been widely used to expand plasma volume and increase practical circulation volume, thereby alleviating cardiocirculatory changes caused by portal hypertension." (PMID 36226354, 2022). "Albumin deficiency is very common in patients with liver disease, indicating impaired liver function." (PMID 35668948, 2022). "In HFpEF patients, low mean arterial pressure, albumin, presumably a marker of nutritional status or liver disease, and the recent use of diuretics were associated with increased 90‐day post‐discharge events." (PMID 35077583, 2022). "From this perspective, albumin levels are a hallmark of liver synthesis, while platelet count is the earliest sign of subclinical portal hypertension and is included in the Baveno criteria for the management of portal hypertension." (PMID 36009789, 2022). "Unlike serum albumin, the serum level of pre-albumin is less affected by the underlying liver disease; it is a well indicator for nutritional status with a shorter half-life than that of serum albumin." (PMID 36439435, 2022). "The American Association for the Study of Liver Diseases (AASLD) Level A recommendation that patients with SBP be managed with albumin is supported by this meta-analysis." (PMID 36721617, 2022). "Serum albumin level is decreased by dilution caused by volume status and conditions with decreased albumin synthesis, such as liver diseases or inflammation." (PMID 35020730, 2022). "A serum albumin ascites gradient ≥ 1.1 g/dL with ascitic total protein < 2.5 g/dL is highly suggestive of the presence of portal hypertension, typically caused by liver disease with an accuracy of approximately 97%." (PMID 36064324, 2022). "For every 2.5 g/L decrease in peripheral albumin, the risk of secondary liver disease complications increased by 89% and the mortality rate increases by 24%–56%." (PMID 35251204, 2022). "For every 10 g/L decrease in peripheral blood albumin, the risk of secondary liver disease complications will increase by 89% and the mortality rate increased by 24%–56%." (PMID 35251204, 2022). "Gastrointestinal bleeding, low serum albumin, poor nutritional status and higher re-exploration rates are associated with increased rates of infection in liver disease." (PMID 36561575, 2022). "Albumin infusions are now essential products for treating hemorrhages and refractory ascites associated with chronic liver cirrhosis, hepatorenal syndrome, and spontaneous bacterial peritonitis." (PMID 33810483, 2021).
liver disease (continued). "A serum–ascites albumin gradient (SAAG) of 1.1 mg/dL or above is suggestive of the presence of portal hypertension and helps to discriminate the underlying condition when the causative disease is unclear." (PMID 34830508, 2021). "Less severe liver disease, represented by lower CP scores and serum bilirubin levels, or higher serum levels of albumin are consistently associated with a higher chance of achieving SVR in decompensated patients." (PMID 34817045, 2021). "Low albumin levels have been associated with advanced liver disease as well as inflammatory diseases." (PMID 33807462, 2021). "The well‐known prognostic impact of the severity of the underlying liver disease was confirmed in this study, reflected by multivariable significance and incorporation of albumin in the PROSASH and PROSASH‐II models." (PMID 31579990, 2020). "Factors as male sex, older age and lower baseline albumin concentration, which are surrogate markers of advanced liver disease resulted independently associated with de novo HCC appearance." (PMID 32279177, 2020). "Albumin synthesis is reduced by the systemic inflammatory response to a tumor, although impaired hepatic synthetic function in advanced liver disease also needs to be considered as an additional cause for reduced serum albumin." (PMID 31614976, 2019). "It has been suggested that ascites accumulation is caused by not only by low albumin levels but also portal hypertension." (PMID 30563565, 2018). "Some diseases and injury cause plasma ALB levels to decrease, including nephrotic syndrome, burns, protein losing enteropathy, malnutrition, and liver disease." (PMID 29789400, 2018). "Numerous clinical observations of mono-infected patients have shown that the serum ALB level is a useful marker of HIV-1-associated liver disease progression." (PMID 29361613, 2018). "This shift to the oxidized state is likely attributed to impaired albumin turnover and oxidative stress caused by hepatic disorders." (PMID 29295548, 2017). "The three who were unaware of their status had identified a risk factor in the questionnaire (tattoo, albumin prior to 1988 and liver disease history)." (PMID 26694960, 2015). "A decrease of albumin can cause tissue edema, which results in more serious liver disease and liver cirrhosis." (PMID 26648983, 2015). "The serum to ascites albumin gradient (SAAG) should be calculated to determine if the ascites is related to portal hypertension or other causes." (PMID 27335837, 2014). "Other variable associated with increased risk for ESRD including younger age, male sex, mild liver disease, cardiovascular disease, lower hemoglobin, lower platelet, lower albumin, higher cholesterol, more advanced CKD stage, and more proteinuria." (PMID 24971499, 2014). "Underlying liver disease was found to have a significant effect on albumin synthesis (P < 0.001), with synthesis by hepatocytes from normal liver significantly higher than both ALD and PBC/PSC (both P < 0.001)." (PMID 24642019, 2014). "The score is composed of six biomarkers (CA 19-9, age, alpha-2- macroglobulin, total bilirubin, platelet count & albumin), which are previously known to have significant diagnostic values of staging hepatic fibrosis and progression of liver disease in general." (PMID 24046790, 2013). "Among the preoperative recipient risk factors were an increased incidence of portal hypertension with ascites, low serum albumin levels, and preoperative hospitalization especially with ventilator support." (PMID 23984168, 2013). "Measurement of serum to ascitic fluid albumin gradient (SAAG) readily differentiates ascites due to portal hypertension and ascites due to other causes." (PMID 21994871, 2011). "Some authors have reported that a reduction in blood levels of albumin may be linked to immunodeficiency, inflammation, or hepatic diseases; and an increase can occur under dehydration conditions." (PMID 40357192, 2025).